GLS2 (glutaminase 2)
Diseases named in the same sentence as GLS2 in open-access papers (continued):
Sharing a sentence is not in itself a finding about the gene and the disease.
cancer (continued). "Therefore, we conclude that GLS2 protein can be shuttled to the nucleus after ectopic expression in human cancer cells; even more, GLS2 protein expressed in cell types with null GLS2 expression (COS-7) was also able to be targeted to the cell nuclei." (PMID 32042057, 2020). "Thus, overexpression or derepression of GLS2 appears as a potential novel therapeutic strategy for certain types of cancer." (PMID 32042057, 2020). "The nuclear and cytosolic (mitochondrial) localizations of GLS2 were also revealed in cancer cells transfected with the c-Myc-tagged GLS2 constructs: Western blots of transfected SH-SY5Y and HepG2 cells showed a clear band in both compartments at the expected molecular mass of taggeg-GLS2." (PMID 32042057, 2020). "Therefore, Gln deprivation and GLS inhibition arrest cancer cells in S phase, while overexpression of GLS2 and exposure to differentiation agents elicit stop at G2/M phase." (PMID 32042057, 2020). "In the current study, we demonstrated that GLS2 can be targeted to the nucleus of cancer cells." (PMID 32042057, 2020). "BothGLS and GLS2 play oncogenic and anti-oncogenic roles depending on the type of cancer." (PMID 30871151, 2019). "In addition, a number of studies have argued that GLS and GLS2-mediated targeted therapies are promising molecular medicines that inhibit cancer development." (PMID 30871151, 2019). "In addition, we found GLS2 is also significantly up-regulated, which indicated an increased uptake of glutamine and suggested increased glutaminolysis in the cancer cells." (PMID 31417867, 2019). "In contrast, studies on GLS2 expression in cancer are relatively limited." (PMID 30871151, 2019). "Previous studies have described the opposing roles that GLS and GLS2 have in cancer." (PMID 31652551, 2019). "Although our analysis demonstrated the association between expression and methylation stratus for GLS2 in some cancers, the analysis does not establish an integrated survival pattern based on its expression, methylation, and functional partners together." (PMID 30871151, 2019). "Moreover, the functional partners of GLS and GLS2 also eventually regulate the survival patterns of patients with certain types of cancer." (PMID 30871151, 2019). "Whereas GLS could be targeted for cancer therapy in patients with breast, esophagus, head-and-neck, and blood cancer, GLS2 could be utilized as a prognostic marker for colon, blood, ovarian, and thymoma cancer." (PMID 30871151, 2019). "Also, as we individually performed an average of the expression of glutaminases over the entire set of tissues, the average expressions of both GLS and GLS2 were slightly lower in cancer tissues than in the normal tissues, as analyzed using the GENT database." (PMID 30871151, 2019). "TAp73 expression is associated with an increased serine/glycine synthesis, production of NADPH and GSH in different cancer models, and glutaminase-2 (GLS-2) and glucose-6-phosphate-dehydrogenase (G6PD) metabolic enzymes have been described as direct TAP73 targets." (PMID 29733853, 2018). "However, knowledge concerning the role of GLS2 in cancer is relatively limited compared with that of GLS." (PMID 28939850, 2017). "We speculate that the abundant glutamine in cancer and the increased GLS2 in response hypoxia may contribute to the enhanced de novo glutathione synthesis." (PMID 26956544, 2016). "Further work is now needed to explore whether targeting Rac1 could be a potential therapy for cancers that have lost GLS2." (PMID 26751560, 2016). "Thus, GLS2 inhibits Rac1 activity, which in turn inhibits migration, invasion and metastasis of cancer cells." (PMID 26751560, 2016).
cancer (continued). "However, given the incredible genetic and microenvironmental diversities across cancer types, do cancer cells exclusively upregulate GLS1 while downregulate GLS2 to sustain glutaminolysis and TCA cycle replenishment?" (PMID 26528759, 2015). "At the same time, GLS2 over-expression reduces the formation of cancer cell colonies." (PMID 26402672, 2015). "Therefore we conclude that GAB/GLS2 inhibition plays a significant role in the anti-cancer mechanisms for compound AV-1." (PMID 25026281, 2014). "Gls2 can regulate antioxidant defense function in cells by decreasing reactive oxygen species (ROS) levels and protect cells from oxidative stress that is known to contribute to genetic instability and cancer initiation and progression." (PMID 24330717, 2013). "Moreover, ectopic expression of Gls2 suppressed cancer cell growth through induction of cell cycle arrest." (PMID 24330717, 2013). "Finally, we examined the biological function of Gls2 and found that restoring Gls2 expression in cancer cells significantly inhibited cancer cell growth and colony formation ability through induction of cell cycle arrest." (PMID 24330717, 2013). "A differential function of GA proteins was first suggested by our group after examination of their pattern of expression in several cancer cell lines and human tumors: GLS isoforms were associated to tumorigenesis while GLS2 were ascribed to cell differentiation." (PMID 22679499, 2012). "Identifying other potential activators of both GAC and GLS2 in cancer cells that can induce filament formation will be important, given that the Pi levels necessary to stimulate enzyme activity and filament formation might not be achievable under many physiological contexts." (PMID 38438397, 2024). "Our findings highlight how ankyrin repeats on GLS2 regulate enzymatic activity, while allosteric activators stabilize, and clinically relevant inhibitors block, filament formation that enables glutaminases to catalyze glutaminolysis and support cancer progression." (PMID 38438397, 2024). "So far, single reports suggest that GLS2 protein may also inhibit the development of other cancers." (PMID 38067269, 2023). "Given the important role of transcription factor Forkhead box C2 (FOXC2) in maintaining stem cell-like features and mesenchymal phenotype, inhibition of FOXC2 expression and subsequent EMT inhibition could restore GLS2 expression as well as glutamine utilization in cancer cells undergoing EMT." (PMID 38017510, 2023). "Thus, two cancer cell models with increased GLS2 expression and nuclear accrual showed a stabilization of the cell cycle in the G2/M phase, in sharp contrast with GLS isoforms whose expression was upregulated in G1 and S phases in association with cell proliferation." (PMID 32042057, 2020). "Moreover, expression of combined GLS and GLS2-centered-signature-gene set might regulate the clinical outcomes in certain cancer." (PMID 30871151, 2019). "Therefore, our findings that GLS2 binds to and inhibits Rac1 raised the possibility that GLS2 may play an important role in suppressing cancer metastasis." (PMID 26751560, 2016). "Indeed, metabolic profiling of human cancer cells revealed that TAp73 regulates serine biosynthesis by transcriptional control of glutaminase-2 (GLS-2), an enzyme that supports glutathione synthesis and enables an effective compensation for an excessive oxidative response." (PMID 26375672, 2015). "Additionally, differential metabolic requirements within specific cancer types might contribute to dictating the final outcome of deregulated GLS2 activities." (PMID 26528759, 2015).
cancer (continued). "Therefore, more work is needed to clarify and demonstrate the role of GLS2 in cancer cell growth." (PMID 25026281, 2014). "Moreover, overexpression of Gls2 led to cancer cell growth inhibition and cell cycle arrest." (PMID 24330717, 2013). "However, although this hypothetical role of GLS2 isoenzyme fits well with its preponderant expression in the liver, this currently only lies on the grounds of speculation, and further efforts are needed to ascertain the role of GLS2 both in physiological conditions and in cancer." (PMID 39796278, 2025). "The cancer-specific expression of GLS1 and the downregulation of GLS2 are based on the specific transcriptional regulation of the two proteins." (PMID 36151426, 2023). "However, we have become increasingly concerned that this term may have been confused with glutaminase 2 (GLS2), leading, in part, to the glutaminase II pathway being unappreciated by most researchers as having a distinct role in l-glutamine addiction in cancers." (PMID 37627015, 2023). "While the expression of GLS2 is commonly repressed in cancers, GLS1 is typically upregulated in cancers, making it an appealing target for cancer therapies." (PMID 34906193, 2021). "For example, overexpression of GLS2 markedly elevated cellular glutamate, GSH, and NADH levels as well as GSH/GSSG in three human cancer cell lines, which correlated with diminution in cellular basal ROS levels, implying reductive stress occurs in these cells." (PMID 31218894, 2020). "The nuclear extracts of these more differentiated and slow-growing GBM cells showed enhanced levels of GLS2, in agreement with the results previously seen in PMA-treated cancer cells." (PMID 32042057, 2020). "Accordingly, the nuclear concentration of GLS2 in HepG2, T98G and SH-SY5Y cancer cells, under basal conditions, is very low compared with the mitochondrial pool of this isoform." (PMID 32042057, 2020). "This fact has been clearly demonstrated in recent studies, where inhibition of cancer proliferation and reversion of the malignant phenotype were achieved by knocking-down GLS or by upregulation of GLS2 expression." (PMID 32042057, 2020). "Given the well-recognized glutamine dependency of many cancer cells, we investigated the roles of GLUL and GLS2 in the relative glutamine independence of the luminal-type cells." (PMID 21852960, 2011). "Our studies suggest that, regardless of the exact role of GLS2 in cancers, cancer researchers interested in studying glutamine addiction in mitotic diseases (including cancers) must take into account the presence of the GTωA pathway in these cells." (PMID 37627015, 2023). "A lack of GLS2 staining was found in the normal tissues, while cancer tissues contained considerable amounts of this protein." (PMID 38067269, 2023). "Regardless of its potential regulatory functions, GLS2 is primarily an enzyme that plays a key role in the altered metabolism of cancer cells." (PMID 38067269, 2023). "Future research should focus on determining whether the mechanism described in HCC is universal and also applies to other types of cancer; moreover, further work is needed to investigate the effects of simultaneous GLS silencing and GLS2 overexpression." (PMID 38067269, 2023).
cancer (continued). "GLS2 is expressed only in the periportal area of the postnatal liver, whereas GLS1 is highly expressed in the kidney, brain, intestine, foetal liver, lymphocytes and cancer cells." (PMID 35538890, 2022). "Unlike the coherent expression tendency of GLS1 in various cancer types, the function pattern of GLS2 seems to be more complex and controversial." (PMID 33194749, 2020). "Although a nucleocytoplasmic location for GLS2 protein was reported in mammalian brain cells, the subcellular localization of GLS2 in human cancer cells has not been yet elucidated." (PMID 32042057, 2020). "To unambiguously demonstrate nuclear targeting of GLS2 proteins in human cancer cells, we decided to use orthogonal methods not relying on the recognition of proteins by anti-GLS2 antibodies." (PMID 32042057, 2020). "The third approach involved an orthogonal method of validation that does not rely on anti-GLS2 antibodies: expression of GLS2-tagged proteins in cancer cells." (PMID 32042057, 2020). "However, GLS2 expression inhibited mammosphere formation by SUM159 cells that overexpress GLS2, and mammosphere formation is correlated with cancer-stem-cell potential." (PMID 31652551, 2019). "It seems clear that GLS2 possesses specific functions differentiating it from GLS, and unravelling them may shed light on both its roles in physiological conditions and its impact on cancer." (PMID 39796278, 2025). "The conversion of glutamine to glutamate by glutaminase (GLS1 or GLS2), which is further transformed to α-ketoglutarate (α-KG) by glutamate dehydrogenase (GLUD1 or GLUD2) or aminotransferases, promotes the TCA metabolism that contributes to sustaining the energy used for cancer cell proliferation." (PMID 35054324, 2022). "Our study demonstrated that in most cancer types, SLC1A5, SLC7A5, SLC7A11, and SLC3A2 were highly expressed and indicative of poorer survival outcomes, while the effects of changes in the expression of GLS2 and GLS depended on the type of cancer under consideration." (PMID 34573287, 2021). "Interestingly, GLS2 directly binds to small GTPase Rac1 independent of its glutaminase activities, which in turn inhibits Rac1 activation to suppress cancer metastasis." (PMID 33681231, 2021). "The nuclear localization of GLS2 may give us new insights to understand non-glutaminolysis functions of this isoenzyme in cancer." (PMID 32042057, 2020). "In contrast, GLS2 was mainly expressed in normal tissue but not in cancer tissue." (PMID 30674873, 2019). "Insteadly, combined treatment with Aza and histone deacetylase inhibitor TSA could increase Gls2 expression in these cancer cells (data not shown), suggesting that histone modification may also mediate Gls2 downregulation in cancer cells." (PMID 24330717, 2013). "GLS2 inhibitors have not received the same attention as their GLS1 counterpart, although early trials have found them to have a potential role in anti-cancer therapies." (PMID 41515893, 2025). "In this study, we found that GLS2 but not GLS1 binds to small GTPase Rac1 and inhibits its interaction with Rac1 activators guanine-nucleotide exchange factors, which in turn inhibits Rac1 to suppress cancer metastasis." (PMID 26751560, 2016).
infection (14 papers, 2018 to 2025). The state of being infected such as from the introduction of a foreign agent such as serum, vaccine, antigenic substance or organism. "Furthermore, gene expression of glycolytic enzymes, lactate, and glutamine metabolism (G6PDH, PKLR, PFKL, LDHA, LDHB, GLS1, GLS2, and GLUL), were upregulated in primary mouse (hACE2) and human hepatocytes upon infection compared to controls." (PMID 35978143, 2022). "Here we found that the pan-GLS/GLS2 inhibitor SU1 was highly effective at blocking HCoV-229E replication, while the GLS-specific compound UP4 was relatively ineffective, consistent with our findings that infection of MRC5 cells predominantly upregulates the GLS2 isoform." (PMID 39662828, 2024).
cardiovascular disease (1 paper, 2023). "Considering that cardiovascular disease (CVD) is the leading cause of mortality in patients with T2DM, targeting GLS2 might be a potential strategy to treat T2DM, which should be evaluated in future studies." (PMID 36865751, 2023).
GLS2 also shares sentences with these, for which no sentence is quoted: acute lymphoblastic leukemia (5 papers); adenocarcinoma (3); Nephropathy (3); Hepatic fibrosis (2); mastitis (2); melanoma (2); prostate carcinoma (2); abscess (1); acute myeloid leukemia (1); Alzheimer disease (1); Anxiety (1); asthma (1); autoimmune disease (1); bacterial infection (1); blood cancer (1); brain injury (1); Burkitt lymphoma (1); chronic osteomyelitis (1); colorectal adenoma (1); coronary artery disease (1); COVID-19 (1); dependence (1); diabetic kidney disease (1); esophageal squamous cell carcinoma (1); Hepatitis (1); hepatocellular adenoma (1); heroin dependence (1); herpes simplex infection (1); Hyperammonemia (1); Impaired glucose tolerance (1).
A further 27 diseases each share a sentence with GLS2 in 1 paper.